ATXN2 (ataxin 2)
Diseases named in the same sentence as ATXN2 in open-access papers (continued):
Sharing a sentence is not in itself a finding about the gene and the disease.
tumor (9 papers, 2015 to 2026). "The results of animal models showed that knocking down ATXN2 decreased the tumor weight and volume of nude mice treated with 5-FU." (PMID 36213324, 2022). "Immunohistochemical staining of nude mouse tumor tissues showed that knockdown of ATXN2 inhibited ki67 expression and promoted cleaved caspase-3 expression." (PMID 36213324, 2022). "We further demonstrated that ATXN2 knockdown with specific siRNA significantly improved nanorod internalization efficiency in Panc-1 cells suggesting that ATXN2 can be a reference for efficiency prediction of nanoparticle delivery to tumor cells." (PMID 31430912, 2019). "Atxn2 is known to show strong physiological expression not only in several neuronal populations such as cerebellar Purkinje cells and spinal motor neurons, but also in liver and in the hepatocyte-like tumor cells Hep G2." (PMID 25721894, 2015).
autosomal dominant disease (3 papers, 2011 to 2019). Autosomal dominant form of disease. "This autosomal dominant disease is caused by an unstable CAG repeat expansion on a coding region of ATXN2 gene, with the consequent expression of abnormally large polyglutamine tract in the ataxin-2 protein." (PMID 29276612, 2017).
infection (2 papers, 2019 to 2021). The state of being infected such as from the introduction of a foreign agent such as serum, vaccine, antigenic substance or organism. "HCV-JFH1 infection redistributes several SG components, including G3BP1, ataxin-2 (ATX2), and poly(A)-binding protein 1 (PABP1), to the HCV replication complex (RC), and co-opts G3BP1 to mediate efficient viral replication by interaction with NS5B and the 5′ end of the HCV minus-strand RNA." (PMID 31037644, 2019).
peripheral neuropathy (1 paper, 2023). A disorder affecting the peripheral nervous system. "SCA2, caused by a CAG expansion in ATXN2 gene, generally present as slowly progressive cerebellar ataxia variably associated with peripheral neuropathy, dystonia, myoclonus, autonomic dysfunction, and slowed horizontal saccades." (PMID 37648940, 2023).
ATXN2 also shares sentences with these, for which no sentence is quoted: Ataxia (19 papers); cerebellar ataxia (12); depression (6); dyslipidemia (5); primary open-angle glaucoma (5); cardiovascular disease (4); alpha-synucleinopathies (3); Friedreich ataxia (3); heart diseases (3); multisystem atrophy (3); myocardial infarction (3); Spastic paraplegia (3); Spinocerebellar ataxia type 3 (3); coronary artery disease (2); disorders of thyroid (2); epilepsy (2); glioblastoma (2); Hypercholesterolemia (2); multiple sclerosis (2); neuropathy (2); peripheral arterial disease (2); Primary lateral sclerosis (2); progressive bulbar palsy (2); schizophrenia (2); spinal muscular atrophy (2); vitiligo (2); Adult onset (1); Alexander disease (1); alopecia areata (1); ataxia telangiectasia (1).
A further 46 diseases each share a sentence with ATXN2 in 1 paper.